NOL3 (nucleolar protein 3)
Description:
[Isoform 1]: May be involved in RNA splicing. [Isoform 2]: Functions as an apoptosis repressor that blocks multiple modes of cell death. Inhibits extrinsic apoptotic pathways through two different ways. Firstly by interacting with FAS and FADD upon FAS activation blocking death-inducing signaling complex (DISC) assembly (By similarity). Secondly by interacting with CASP8 in a mitochondria localization- and phosphorylation-dependent manner, limiting the amount of soluble CASP8 available for DISC-mediated activation (By similarity). Inhibits intrinsic apoptotic pathway in response to a wide range of stresses, through its interaction with BAX resulting in BAX inactivation, preventing mitochondrial dysfunction and release of pro-apoptotic factors. Inhibits calcium-mediated cell death by functioning as a cytosolic calcium buffer, dissociating its interaction with CASP8 and maintaining calcium homeostasis. Negatively regulates oxidative stress-induced apoptosis by phosphorylation-dependent suppression of the mitochondria-mediated intrinsic pathway, by blocking CASP2 activation and BAX translocation (By similarity). Negatively regulates hypoxia-induced apoptosis in part by inhibiting the release of cytochrome c from mitochondria in a caspase-independent manner (By similarity). Also inhibits TNF-induced necrosis by preventing TNF-signaling pathway through TNFRSF1A interaction abrogating the recruitment of RIPK1 to complex I (By similarity). Finally through its role as apoptosis repressor, promotes vascular remodeling through inhibition of apoptosis and stimulation of proliferation, in response to hypoxia (By similarity). Inhibits too myoblast differentiation through caspase inhibition (By similarity).
Synonyms: Myp; Nop30; ARC; NOP; CARD2; FCM; MYOCL1
Tractability: PROTAC: UniProt records ubiquitination sites on it; its protein half-life has been measured.
Gene: Protein-coding gene on chromosome 16 (67,170,154 to 67,176,189, forward strand). Ensembl gene ENSG00000140939.
Subcellular location: Nucleus, nucleolus (Isoform 1); Cytoplasm (Isoform 3); Cytoplasm (Isoform 2); Mitochondrion; Sarcoplasmic reticulum; Membrane
Subcellular location (Human Protein Atlas): Cytosol; Nucleoplasm
Gene Ontology:
Molecular function: calcium ion binding; caspase binding; cysteine-type endopeptidase inhibitor activity involved in apoptotic process; identical protein binding; protein binding; death receptor binding; RNA binding; death effector domain binding; signaling receptor binding
Biological process: mRNA splice site recognition; negative regulation of apoptotic process; negative regulation of extrinsic apoptotic signaling pathway; negative regulation of oxidative stress-induced intrinsic apoptotic signaling pathway; negative regulation of release of cytochrome c from mitochondria; protein complex oligomerization; release of sequestered calcium ion into cytosol by sarcoplasmic reticulum; negative regulation of hypoxia-induced intrinsic apoptotic signaling pathway; negative regulation of intrinsic apoptotic signaling pathway; RNA splicing; blood vessel remodeling; cardiac muscle cell apoptotic process; intrinsic apoptotic signaling pathway; negative regulation of cardiac muscle cell apoptotic process; negative regulation of mitochondrial membrane permeability involved in apoptotic process; negative regulation of muscle atrophy; negative regulation of programmed necrotic cell death; negative regulation of signal transduction; negative regulation of striated muscle cell apoptotic process; negative regulation of tumor necrosis factor-mediated signaling pathway; regulation of apoptotic process; regulation of intracellular signal transduction; regulation of non-canonical NF-kappaB signal transduction; response to ischemia
Cellular component: cytoplasm; cytosol; nucleoplasm; mitochondrion; nucleolus; sarcoplasmic reticulum; membrane; sarcoplasm
Genetic constraint (gnomAD): Loss-of-function variants: 19 observed, 16.33 expected, observed/expected ratio (o/e) 1.16, 90% interval 0.81 to 1.69. The upper end of that interval is the gene's LOEUF score, 1.69, which puts it in group 6 of 6, group 1 being the genes least tolerant of losing a copy. Missense variants: 290 observed, 277.14 expected, observed/expected ratio (o/e) 1.05, 90% interval 0.95 to 1.15. Synonymous variants: 127 observed, 130.98 expected, observed/expected ratio (o/e) 0.97, 90% interval 0.84 to 1.12.
Homologues: Orthologues: macaque NOL3 (95% identical), rabbit NOL3 (88% identical), mouse Nol3 (82% identical), dog NOL3 (81% identical), guinea pig NOL3 (79% identical), rat Nol3 (75% identical), chimpanzee NOL3 (53% identical). Paralogues in human: CARD6 (33% identical).
Diseases named in the same sentence as NOL3 in open-access papers:
NOL3 is named in the same sentence as 35 diseases in open-access papers, as found by Europe PMC text mining. Sharing a sentence is not in itself a finding about the gene and the disease. The quoted sentences say what the papers report.
breast carcinoma (5 papers, 2007 to 2019). "In the breast cancer model, the major effect of nol3 deletion on tumor growth was to reduce rates of tumor cell proliferation (mechanism not known), while basal rates of apoptosis were not affected." (PMID 26709830, 2015). "Further, deletion of nol3, which encodes ARC, in the context of a transgenic mouse model of breast cancer, ameliorates tumor growth, invasion, metastasis, and chemoresistance." (PMID 26709830, 2015). "NOL3, an apoptosis suppressor limited to terminally differentiated cells, is induced in human breast cancer and confers chemo-and radiation-resistance." (PMID 20642818, 2010). "The apoptotic genes SPP1 and SFRP1 are candidate tumor suppressors for various cancers; AXL gene is a proto-oncogene, and NOL3 (ARC, apoptosis repressor with CARD domain) is induced in human breast cancer and confers chemo- and radiation-resistance." (PMID 19455236, 2007). "Since ARC inhibits apoptosis in both transformed β-cells and breast cancer cells, why did nol3 deletion not affect rates of apoptosis in insulinomas and breast tumors?" (PMID 26709830, 2015). "ARC abundance increases in multiple human cancers, and the absence of an effect of nol3 deletion on MEN1 tumor load in this study contrasts with the amelioration of tumor growth (as well as metastasis) resulting from nol3 inactivation in a genetic mouse model of breast cancer." (PMID 26709830, 2015).
Hyperglycemia (2 papers, 2017 to 2022). An increased concentration of glucose in the blood. "The generation of mice with a floxed Nol3 allele will be necessary to dissect contributions to the hyperglycemia from various tissues." (PMID 28765602, 2017).
autism (1 paper, 2015). Persistent deficits in social interaction and communication and interaction as well as a markedly restricted repertoire of activity and interest as well as repetitive patterns of behavior. "Some have been associated with neurodevelopmental disorders: schizophrenia (DIXDC1, ARVCF, MAGI2, ZIC2), ADHD (attention deficit/hyperactivity disorder) (TCERG1L), movement disorders (NOL3, TP53INP2), Huntington’s disease (H2AFY2, AGPAT1), Parkinson’s disease (LMX1B), and autism (PLXNA4, WNT2)." (PMID 25748564, 2015).
breast tumors (1 paper, 2015). "Consistent with this hypothesis, nol3 deletion markedly exacerbates apoptosis when mice harboring breast tumors are treated with chemotherapeutic agents." (PMID 26709830, 2015).
COVID-19 (1 paper, 2025). A disease caused by infection with severe acute respiratory syndrome coronavirus 2. "Overlapping genes for TSA and COVID-19 were SERPINH1, LPAR1, and TCEA2, and overlapping genes for TSA and MDD were NOL3, LPAR1, and HSPA6." (PMID 40918512, 2025).
glioma (1 paper, 2017). A benign or malignant brain and spinal cord tumor that arises from glial cells (astrocytes, oligodendrocytes, ependymal cells). "We have also identified a four RBP (NOL3, SUCLG1, HERC5 and AFF3) signature, having a unique expression pattern in glioma stem-like cells (GSCs), to be an independent poor prognostic indicator in GBM." (PMID 28035070, 2017).
insulinomas (1 paper, 2015). "In contrast, nol3 deletion affected neither basal rates of cell proliferation nor cell death in MEN1 insulinomas, which likely accounts for the absence of an effect of loss of ARC in these tumors." (PMID 26709830, 2015).
lymph node metastasis (1 paper, 2020). "We also found that NOL3 was significantly overexpressed in patients with lymph node metastasis, distant metastasis, and at a late clinical stage." (PMID 33193701, 2020).
malaria (1 paper, 2021). Malaria is a serious and sometimes fatal disease caused by a parasite that commonly infects a certain type of mosquito which feeds on humans. "Nuclear poly(A) binding protein 2 (NAB2), THO complex subunit 4 (THO4), nucleolar protein 3 (NPL3), G-strand binding protein 2 (GBP2) and serine/arginine-rich splicing factor 1 (SR1) are involved in nuclear mRNA export in malaria parasites." (PMID 34604117, 2021).
meningioma (1 paper, 2017). A generally slow growing tumor attached to the dura mater. "The trends of gene expression profiles of candidates such as EFCAB2, EPS8L1, NOL3, PAIP1 and SNX1 showed elevated expression in meningiomas compared to controls, while CAMK2N1, CRYM and PRPSAP2 showed decreased expression levels in meningiomas compared to the controls." (PMID 28938569, 2017).
migraine (1 paper, 2021). "NOL3 mutation may also cause delayed AoM by a loss or decrease-of-function in neuronal excitability, although the exact pathogenesis associating NOL3 and migraine needs further investigation." (PMID 34380431, 2021).
muscular dystrophy (1 paper, 2013). Muscular dystrophy (MD) refers to a group of more than 30 genetic diseases characterized by progressive weakness and degeneration of the skeletal muscles that control movement. "To further investigate the molecular regulators of myofiber death in muscular dystrophy, we utilized a genetic approach by deleting the Nol3 gene (encodes Arc, apoptosis repressor with a card domain) in several muscular dystrophy mouse models." (PMID 24312627, 2013). "The number of fibers with centrally located nuclei was also increased in muscle from Nol3-/-Sgcd-/- mice, suggesting that the loss of Arc in muscular dystrophy results in more myofibers undergoing degeneration." (PMID 24312627, 2013). "Because Arc has been identified as an inhibitor of apoptotic death, quadriceps and gastrocnemius muscles from 4 week-old Nol3-/-Sgcd-/- mice were examined by TUNEL staining to identify if Arc deficiency enhances this molecular index of presumed apoptotic cell death in muscular dystrophy." (PMID 24312627, 2013). "Here we crossed Nol3-/- mice with either Sgcd-/- or Lama2-/- muscular dystrophy mouse models to create dystrophic skeletal muscles that are also devoid of Arc." (PMID 24312627, 2013).
myelofibrosis (1 paper, 2025). A partial or complete replacement of the bone marrow stroma by fibrous tissue. "The lack of NOL3 may trigger the development of myeloid proliferative tumors resembling primary myelofibrosis, with the underlying mechanism linked to the activation of the JAK-STAT pathway." (PMID 41040951, 2025).
myocardial infarction (1 paper, 2013). Gross necrosis of the myocardium, as a result of interruption of the blood supply to the area, as in coronary thrombosis. "In the heart, Nol3-/- mice showed increased signs of cell death, fibrotic remodeling and injury area following myocardial infarction (MI) or ischemia-reperfusion (IR) providing further support for Arc’s protective role against cell death." (PMID 24312627, 2013).
nasopharyngeal carcinoma (1 paper, 2020). A carcinoma arising from the nasopharyngeal epithelium. "Overexpression of NOL3 was also related to poor prognosis of nasopharyngeal carcinoma patients." (PMID 33193701, 2020).
pancreatic cancer (1 paper, 2019). "Several other proteins in this group also displayed greater induction under serum-free conditions (NOL3, NCS1, CD151), suggesting synergistic effects of hypoxia and nutrient deprivation on pancreatic cancer cell development and angiogenic activity." (PMID 31666928, 2019).
prostate carcinoma (1 paper, 2023). A carcinoma that arises from epithelial cells of the prostate gland. "With siRNA screens, several of these were indicated in survival (DDX6, EIF4A3, PABPN1), growth (e.g., EIF5A, HNRNPH2, LRRC47, and NVL), and migration (e.g., NOL3 and SLTM) of prostate cancer cells." (PMID 37591798, 2023). "DDX6, NOL3, and RRP9 showed differential expression in RNA and protein data between primary cancer and CRPC, suggesting that these RBPs are regulated post‐transcriptionally in prostate cancer." (PMID 37591798, 2023).
tumor (11 papers, 2007 to 2025). "For example, menin might repress nol3 transcription through inhibition of a transcriptional activator whose presence is restricted to tumor-susceptible tissues." (PMID 26709830, 2015). "To summarize, NOL3 fulfills multiple roles across various tumor types, including enhancing cell proliferation, controlling apoptosis, and influencing signaling pathway regulation." (PMID 41040951, 2025). "Researches showed a tumor suppressor role of NOL3 in the pathogenesis of myeloid malignancies." (PMID 35241019, 2022). "The anti-tumour effects of Rec8 are caused by downregulation of cell growth-related genes (G6PD, SLC2A1, NOL3, MCM2, SNAI1, and SNAI2) and also by upregulation of both apoptosis or migration inhibitors (Gadd45G and LDHA) and tumour inhibitors (PinX1, IGFBP3, and ETS2)." (PMID 36139540, 2022). "Immunohistochemical staining results displayed that NOL3 and UPF3B were upregulated in CRC tumor tissues." (PMID 33193701, 2020). "The results indicated that NOL3 and UPF3B were overexpressed in CRC tumor tissues compared with normal tissues." (PMID 33193701, 2020). "For rs9929218 at 16q22.1, two genes were observed to have a difference in expression levels by genotype: nucleolar protein 3 (NOL3; q-value = 0.017) and DEAD box polypeptide 28 (DDX28, q-value = 0.046), in adjacent normal but not tumor tissue." (PMID 22363440, 2012).
cancer (8 papers, 2007 to 2023). A tumor composed of atypical neoplastic, often pleomorphic cells that invade other tissues. "NOL3 is an apoptosis suppressor and is related to chemoresistance and radiotolerance in cancer cell." (PMID 35736153, 2022). "A previous ChIP on chip analysis suggested that menin binds promoter sequences of nol3, encoding ARC, which is a cell death inhibitor that has been implicated in cancer pathogenesis." (PMID 26709830, 2015). "Finally, NOL3 might be modulated by known cancer signaling proteins including Ras and HIF-1, and the lncRNA PCAT6, in CRC." (PMID 33193701, 2020). "Several other candidate genes were found to be undetectable in whole blood, while most of the genes that were detectable (EGLN3, CAV2, ESM1, TMEM45A, NOL3, FABP7) did not exhibit significant dysregulation in expression between cancer and healthy PAXgene samples." (PMID 32013938, 2020).
NOL3 also shares sentences with these, for which no sentence is quoted: Arthritis (1 paper); asthma (1); atherosclerosis (1); colorectal cancer (1); diabetes (1); eosinophilia (1); gastric cancer (1); Huntington disease (1); hypothyroidism (1); leukaemia (1); lung carcinoma (1); movement disorder (1); neurodevelopmental disorder (1); Obesity (1); Parkinson disease (1); schizophrenia (1).